EVX2 (even-skipped homeobox 2)
Synonyms: EVX-2
Tractability: No criterion of Open Targets' tractability assessment is met for any kind of drug.
Gene: Protein-coding gene on chromosome 2 (176,077,472 to 176,083,962, reverse strand). Ensembl gene ENSG00000174279.
Subcellular location: Nucleus
Gene Ontology:
Molecular function: protein binding; sequence-specific double-stranded DNA binding; DNA-binding transcription factor activity, RNA polymerase II-specific; RNA polymerase II cis-regulatory region sequence-specific DNA binding; DNA binding
Biological process: regulation of transcription by RNA polymerase II; regulation of DNA-templated transcription
Cellular component: chromatin; nucleus
Genetic constraint (gnomAD): Loss-of-function variants: 14 observed, 17.83 expected, observed/expected ratio (o/e) 0.79, 90% interval 0.52 to 1.23. The synonymous counts are far from expectation, so gnomAD's model fits this gene poorly and the ratio says little. Missense variants: 710 observed, 575.25 expected, observed/expected ratio (o/e) 1.23, 90% interval 1.16 to 1.31. Synonymous variants: 354 observed, 265.15 expected, observed/expected ratio (o/e) 1.34, 90% interval 1.22 to 1.46.
Homologues: Orthologues: chimpanzee EVX2 (99% identical), macaque EVX2 (99% identical), pig EVX2 (97% identical), dog EVX2 (97% identical), rat Evx2 (95% identical), mouse Evx2 (94% identical), rabbit EVX2 (74% identical), tropical clawed frog evx2 (69% identical), zebrafish evx2 (69% identical), guinea pig EVX2 (50% identical). Paralogues in human: EVX1 (45% identical), ARX (19% identical), PAX7 (16% identical), PAX3 (16% identical), PITX3 (14% identical), OTX1 (14% identical), PITX2 (14% identical), UNCX (14% identical), ALX4 (14% identical), OTX2 (14% identical), PITX1 (14% identical), RAX (14% identical), and 38 more.
Diseases named in the same sentence as EVX2 in open-access papers:
EVX2 is named in the same sentence as 11 diseases in open-access papers, as found by Europe PMC text mining. Sharing a sentence is not in itself a finding about the gene and the disease. The quoted sentences say what the papers report.
lung carcinoma (3 papers, 2020 to 2024). "This gene was found highly methylated in lung cancer, where a role for EVX2 as a methylation biomarker for early detection of the disease has been suggested." (PMID 32156068, 2020). "EVX2 is recently revealed to be regulated by methylation and serve as a methylation biomarker for lung cancer." (PMID 32821544, 2020).
cystic teratoma (1 paper, 2024). "The most interesting findings of this study are amplifications of EVX2, HOXD13, HOXD12, HOXD11, HOXD10, and HOXD9 on a 41.6 kb segment of 2q31.1 in all nine mature cystic teratomas." (PMID 38907278, 2024). "In summary, amplifications of EVX2, HOXD13, HOXD12, HOXD11, HOXD10, and HOXD9 on 2q31.1, NDUFV1 on 11q13.2, and RPL10, SNORA70, DNASE1L1, TAZ, ATP6AP1, and GDI1 on Xq28 were found in all nine mature cystic teratomas in this study." (PMID 38907278, 2024). "Amplifications and deletions of large DNA fragments were observed in some samples, while amplifications of EVX2 and HOXD9-HOXD13 on 2q31.1, NDUFV1 on 11q13.2, and RPL10, SNORA70, DNASE1L1, TAZ, ATP6AP1, and GDI1 on Xq28 were found in all nine mature cystic teratomas." (PMID 38907278, 2024).
gastric cancer (1 paper, 2021). A primary or metastatic malignant neoplasm involving the stomach. "A negative correlation was found between VSTM2L and CIMP, and a CIMP-related gene signature comprising six genes (VSTM2L, CST6, SLC7A2, RAB3B, IGFBP1, and EVX2) stratified gastric cancer patients into high‐ and low-risk groups with distinct prognoses." (PMID 35155565, 2021).
neuroblastoma (1 paper, 2020). Neuroblastoma (NB) is the most common solid, extracranial childhood tumor. "Functional studies are required to elucidate the roles of SMIM28, EVX2 and POU6F2 in high-risk neuroblastoma." (PMID 33245713, 2020).
prostate carcinoma (1 paper, 2019). A carcinoma that arises from epithelial cells of the prostate gland. "In the colon cfDNA pool, TFs EVX2, DLX2, HNF1A, HNF4A, and HNF4G and TFs AR and HOXB13 in the prostate cancer cfDNA pool had increased accessibilities, whereas FOXA1 exceeded the >5 z-score threshold in both the prostate and breast pool." (PMID 31604930, 2019).
squamous cell carcinoma (1 paper, 2011). A carcinoma arising from squamous epithelial cells. "Methylation of CALCA, CDH1, DAPK1, and EVX2 was more common in squamous cell carcinomas (SCC) compared to adenocarcinomas (ADC)." (PMID 21507233, 2011).
synpolydactyly (1 paper, 2024). A joint presentation of syndactyly (fusion of digits) and polydactyly (production of supernumerary digits). "A 117 kb microdeletion at the 5’ end of the HOXD gene cluster, which includes EVX2 and HOXD9-HOXD13 genes, causes synpolydactyly." (PMID 38907278, 2024).
tumor (2 papers, 2011 to 2019). "We observed already statistically significant different accessibilities between healthy controls and COAD samples for TFs HNF4A and DLX2 and the other TFs, GRHL2, EVX2, LYL1, and PU.1 showed statistically significant differences at a 1% tumor level." (PMID 31604930, 2019). "Next, we compared accessibilities in subsamples with different tumor fractions for TFs selected based on our previous ATAC-seq and nucleosome plasma mapping, i.e., GRHL2, EVX2, DLX2, HNF4A, LYL1, and PU.1." (PMID 31604930, 2019). "In addition, this study also involved two new methylation markers, EVX2 and PAX6, which were highly specific for tumor-associated methylation, and little or no methylation was observed in tumor-adjacent normal lung tissue." (PMID 21507233, 2011).
EVX2 also shares sentences with these, for which no sentence is quoted: adenocarcinoma (1 paper); heart defects (1); teratoma (1).